IL6 (interleukin 6)
Diseases named in the same sentence as IL6 in open-access papers (continued):
Sharing a sentence is not in itself a finding about the gene and the disease.
tumor (continued). "Our approach of an intravenous injection of Luciferase-expressing human DLBCL cells in human IL6 transgenic NSG mice demonstrated rapid tumor cell engraftment and expansion, showing unique organ infiltration patterns reflecting the DLBCL subtype." (PMID 39272864, 2024). "Tumor-derived factors (i.e., IL-6, IL-10, IL-1β, PGE2, VEGF, GM-CSF, M-CSF, and IFN-γ) have been reported to induce MDSCs." (PMID 39272914, 2024). "NF-κB activation leads to the release of several cytokines, including IL-6, IL-12, IL-17, IL-18, and tumor necrosis factor-alpha, contributing to persistent inflammation within the tumor microenvironment." (PMID 38256183, 2024). "IL-6 signaling drives the proliferation, survival, invasiveness, and metastasis of tumor cells, while strongly suppressing the antitumor immune response." (PMID 38900577, 2024). "Tumor endothelial cells secrete IL-6 and CSF-1 which promote anti-tumor alternative macrophage polarization by triggering Akt1/mTOR pathway, resulting in anti-inflammatory and pro-tumorigenic macrophage activation." (PMID 38576482, 2024). "This staining technique was applied to the 4T1 tumor samples, and it was found that IL-6 KO tumors had a higher concentration of intratumoral MCs compared to the WT control tumors." (PMID 39195287, 2024). "Adipokines and inflammatory cytokines produced by adipocytes and macrophages, such as adiponectin, leptin, TNFα, and IL6, can promote tumour growth by cell proliferation, migration, and neo-angiogenesis." (PMID 38339282, 2024). "As early as 1998, IL-6 levels were found to be greater in CRC tumour tissues than in normal control tissues." (PMID 38504172, 2024). "To investigate the effect of IL6 on tumor infiltration of cytotoxic T cells and NK cells in MOC2 and TC-1 tumors, we determined the number of intratumoral CD8+ T cells and CD161+ NK cells in the presence or absence of αIL6 treatment." (PMID 38468260, 2024). "In our study, we evaluated the concentration of circulating inflammatory-mediated cytokines (IL-10, IL-6, and IL-1ß) in all groups at different time intervals before and after tumor resection." (PMID 38662232, 2024). "MyCAFs, characterized by high expression of α-SMA and low expression of IL6, are activated by direct contact between tumor cells and PSCs." (PMID 39195299, 2024). "These factors coordinate to produce tumour growth-promoting cytokines, including tumour necrosis factor-α, interleukin-1β and IL-6." (PMID 39421170, 2024). "IL-6 is secreted by various cells such as mesenchymal cells, endothelial cells, fibroblasts, and tumor cells." (PMID 38649462, 2024). "The IL-6/JAK/STAT3 signaling directly promotes tumor progression, severely hampering antitumor immunity." (PMID 38274367, 2024). "It has been shown that tumor-derived exosomes bring about the inhibition of the differentiation by secreting IL-6, and activating Stata3 signaling too." (PMID 38391950, 2024). "Taken together, our results suggest that the combination of dasatinib/quercetin, although it is an effective senolytic treatment, has an undesirable side effect of promoting IL-6-dependent EMT in tumor cells." (PMID 38612842, 2024). "In mice bearing the ECs with IL-6 deletion, there was a 70% volumetric reduction of the tumor, and 20% of the mice showed complete eradication of tumor." (PMID 39512605, 2024). "We plotted the concentrations of Vpr and IL-6 and found that these molecules are well correlated in the non-tumor group (r = 0.266, P = 0.0095)." (PMID 38166062, 2024). "IL-6, in this context, promotes epithelial-mesenchymal transition (EMT), a characteristic of tumor cells associated with invasion and metastasis." (PMID 38709264, 2024). "IL-6 is considered a pleiotropic molecule that promotes tumor transformation and can, particularly, promote tumor cell invasion and metastasis." (PMID 38834834, 2024).
tumor (continued). "IL-6 has been said to have anti-inflammatory properties, but it plays a crucial role in increasing inflammation and immunological responses during tumor development." (PMID 38803729, 2024). "Immunofluorescence and in situ hybridization staining further validated the elevated expression of IL6 and Gremlin 1 within the tumor microenvironment." (PMID 39872866, 2024). "The overexpression of the marker gene RGS-5 and IL-6 stimulation of tumor-derived pericytes mediate CD4+ T-cell anergy in vitro, elicited by the upregulation of anergy-related factors (dgkα, erg2, and erg3)." (PMID 39086395, 2024). "In primary tumor cells, IL-6 expression is increased by DNA demethylation of its promoter via ten-eleven translocation 2 (Tet2)." (PMID 39199304, 2024). "In multiple tumor models, tumor promotion by IL-17, IL-6, and CSF3 depends, at least in part, upon accumulation of MDSCs." (PMID 39338937, 2024). "As a third‐generation selective estrogen receptor modulator, bazedoxifene has been proven to inhibit tumor cell growth and migration by inhibiting the IL6/GP130 signaling pathway." (PMID 39152779, 2024). "Further, our study indicates that IL-6-secreting CAFs play a crucial role in promoting tumor progression." (PMID 38892065, 2024). "In HER2-positive breast cancer, PHF8 influences the tumor microenvironment by regulating cytokine IL-6 production and promoting T cell migration into the tumor." (PMID 39311138, 2024). "In the event of hepatocarcinogenesis and progression, increased serum IL-6 level and activated IL-6/STAT3 signaling is highly associated with early tumor recurrence and poor prognosis of HCC patients." (PMID 38890694, 2024). "Tumor-promoting SASP effects are associated with pro-inflammatory SASP factors (e.g., IL-6 and IL-8), which promote epithelial-to-mesenchymal transition, recruitment of tumor-promoting macrophages, and suppression of cytotoxic T cell function." (PMID 38415245, 2024). "The oncogene SERPINE2-derived circRNA, named cSERPINE2, functionally shuttles to TAMs via tumor exosomes and enhances the secretion of IL-6, leading to increased proliferation and invasion of breast cancer cells." (PMID 39068459, 2024). "The role of the IL-6 pathway has been described in many cancers, linked to formation of an inflammatory TME, in addition to effects in the tumour cells themselves via the JAK/STAT signalling pathway." (PMID 38803348, 2024). "It is important to counteract the influence of IL-6 on helper T cells in order to preserve the balance of Th1/Th2 and bolster anti-tumor immunity." (PMID 38828409, 2024). "By activating fibroblasts in remote organs, EVs-transferred integrin beta-like 1 (ITGBL1) facilitates metastatic tumor cell growth by triggering the release of pro-inflammatory cytokines IL-6 and IL-8." (PMID 38741166, 2024). "These inflammatory agents, which encompass IL-1, IL-6, and IL-8, have been identified as key players in facilitating osteoclastogenesis, promoting tumor proliferation, and fostering angiogenesis." (PMID 39125732, 2024). "To investigate the potential predictive role of cytokines and tumor markers in immunotherapy efficacy, we conducted a correlation analysis between blood IL-6/IL-8 concentrations and tumor markers in AGC patients receiving immunochemotherapy." (PMID 38774604, 2024). "Animal studies have illustrated that adrenaline and IL-6 released during exercise facilitate NK cell mobilization, redistribution, activation, and enhanced infiltration into tumor sites." (PMID 39346906, 2024). "Apart from chemokines, the anti-tumor capacity of CD8+T cells was largely regulated by pro-inflammatory cytokines such as IL-6 and TNF-α." (PMID 38291473, 2024). "Studies have shown that inflammatory cytokines such as TNF-α, IL-6, and IL-1β can activate cellular signaling pathways that promote tumor survival and growth." (PMID 39339213, 2024).
tumor (continued). "Following this, necrotized cancer cells liberate an ensemble of damage-associated molecular patterns (DAMPs), IL-8, IL-6, CCL2, and CXCL1, orchestrating microglial recruitment, thereby fostering tumor invasiveness and culminating in a self-reinforcing loop." (PMID 38217037, 2024). "Both IL-6 and IL-8 contribute to the recruitment of myeloid-derived suppressor cells to the TME, hindering the anti-tumor activity of cytotoxic T cells, and have been associated with poor clinical outcomes across different tumor types." (PMID 39465007, 2024). "Elevated concentrations of proinflammatory mediators, including interleukin 6 (IL-6), IL-8, IL-10 in CF tumor tissue prompted the use of tocilizumab and bevacizumab, achieving a decrease in cystic disease after initiation of combination therapy." (PMID 39634188, 2024). "The secretion of CCL2 by UBC cells and IL-6 by macrophages within the TME acted in concert to augment tumor stemness and promote UBC progression." (PMID 39479456, 2024). "Since we detected increased IL6 expression in the tumors of KPT mice, we also assessed the causal consequences of this correlation and found that KPT organoid tumor allografts grew slower in IL-6-deficient hosts." (PMID 39128004, 2024). "As previously reported, IL-6 binds to receptors on the surface of tumour cells and activates gp130 to phosphorylate STAT3." (PMID 38504172, 2024). "In tumor-bearing mice, acute (up to a 29-fold increase) IL-6 skeletal muscle levels led to a significant decrease in tumor volume and an increase in natural killer (NK) cells infiltrating the tumor." (PMID 39683624, 2024). "Interleukin-6 (IL-6), a multifunctional signaling molecule, is primarily produced by immune cells, epithelial cells, and tumor cells." (PMID 39911236, 2024). "To investigate the potential therapeutic role of the circNOX4/IL-6 axis, we established xenograft tumor models and performed experimental therapy with IL-6 antibodies." (PMID 38459511, 2024). "IL‐6 can act on the brain to regulate appetite, and inhibition of IL‐6 signalling suppresses anorexia in tumour‐bearing mice." (PMID 38302863, 2024). "Polyphenols like curcumin (from turmeric) and quercetin (from fruits and vegetables) reduce the secretion of cytokines driving inflammation, such as TNF-α, IL-6, and IL-1β, related to prolonged inflammation response and tumor progression." (PMID 39683540, 2024). "In patients with cancer, IL-6 is recognized for its role in promoting tumor growth and treatment resistance." (PMID 39272832, 2024). "Senescent tumor cells derived IL-6 induced the upregulation of TAMs CD73 expression through the JAK/STAT3 signaling pathway." (PMID 38323313, 2024). "Among the 9 ICDRGs, research has demonstrated that IL6 plays a crucial role in tumor progression within the immune microenvironment." (PMID 38461430, 2024). "Both tumor cells and BMAs can produce IL-6, which promotes tumor cell proliferation, induces OC activation, and downregulates OB activity." (PMID 38571500, 2024). "This study indicates that IL-6 in the tumor microenvironment is essential for intercellular communication." (PMID 38422751, 2024). "Studies have highlighted the role of particular ILs, such as IL-1, IL-6, and IL-11, in enhancing osteoclastogenesis, tumor growth, and bone deterioration, underscoring their potential as targets for therapeutic intervention to hinder bone metastases." (PMID 39125732, 2024). "A dual approach of combining IL6 blockade with anti-estrogen hormonal therapy indeed arrested tumor growth." (PMID 39766086, 2024). "CAFs can regulate tumor microenvironment by releasing cytokines (IL-6) and chemokines (CCL2 and CXCL10)." (PMID 38896161, 2024). "IDO1 expression can be either triggered as a counter regulatory response to cytokines like IL-1β and IL-6 released from tumor-infiltrating immune cells or maintained through tumor-intrinsic oncogenic signaling." (PMID 38218942, 2024).
tumor (continued). "These interactions contribute to increased tumor heterogeneity and promote the secretion of pro-tumorigenic cytokines like IL-6, creating an immunosuppressive microenvironment." (PMID 38892065, 2024). "Tumor cells predominantly express Th2 type cytokines, such as IL-4, IL-6, and IL-10 which aid tumor cells in evading immune destruction by inhibiting the differentiation of CD8+ T cells." (PMID 38255791, 2024). "In the TIM, the IL-6/JAK/STAT3 signaling pathway drives tumor cell proliferation, survival, invasion, and metastasis, while concurrently suppressing anti-tumor immune responses." (PMID 39068665, 2024). "This activation leads to the expression of interleukins, such as IL-6, for tumor cell survival, as well as angiogenic factors, like VEGF and IL-8." (PMID 38674385, 2024). "Other non-malignant cells in the surrounding area can also have increased STAT3 activation since STAT3 can become activated in the tumor microenvironment in part due to the presence of cytokines that activate this protein, like IL-6." (PMID 38611065, 2024). "The upregulation of xCT induces ferroptosis resistance and tumor progression, suggesting IL-6 as a novel oncogenic ferroptosis inhibitor." (PMID 38800384, 2024). "Our in vivo differential gene expression analysis revealed a downregulation of the gene IDO1 which codes for a tumor-promoting enzyme and the gene for the metastasis-promoting cytokine IL6 was also downregulated." (PMID 39335552, 2024). "Conversely, a pervasive decrement was witnessed in the expression of GABARAPL1, MAP1LC3C, VTN, and IL6 in nearly all tumor specimens relative to their paired normal tissue counterparts." (PMID 38460947, 2024). "According to studies, IL-6 is involved in tumor development, differentiation, apoptosis, immune response, and drug resistance." (PMID 39099925, 2024). "Mechanistically, VPS35 activates FAK-SRC kinases through integrin-mediated outside-in signalling, which results in the activation of YAP and, subsequently, IL-6 expression in tumour cells." (PMID 37950040, 2024). "Remarkably, neutralization of IL-6 in the brain of tumor-bearing mice with an anti-IL-6 antibody attenuates cachexia and the hyperactivity in the AP network, and markedly prolongs lifespan." (PMID 38824130, 2024). "We also showed that ER‐α36 interacted with p65 and reduced IL‐6 production in tumours in these TAMs." (PMID 37974543, 2024). "In the present study, we have also shown that the spatial distribution of IL6 is important in tumour progression." (PMID 39766336, 2024). "When compared with Mock-T cell treated controls, circulating IL-6 was significantly elevated in tumor-bearing Cd248WT, E3K CAR-T cell treated mice." (PMID 38413223, 2024). "High levels of cholesterol PD and its association with low IL-6 and IL-10 levels, could reflect a low systemic inflammatory state (or a “good” chronic inflammation state) and might favorably condition the proficiency of the tumor microenvironment to respond to ICIs." (PMID 38989743, 2024). "IL-6 is also one of the major cytokines in the tumor microenvironment; its overexpression has been reported in almost all types of tumors." (PMID 38892006, 2024). "Interleukin-6, which influences M2 polarisation of macrophages, had a correlation coefficient of ρ 0.51 with tumour volume." (PMID 38480935, 2024). "The TAMs release IL-6, and other cytokines (e.g., IL-1β) that promote tumor progression [Buonfiglio and Hambardzumyan, 2021]." (PMID 39512605, 2024). "IL-6 has pleiotropic effects on immune cells, which contributes to its role in tumor promotion and as a regulator of MDSC activity." (PMID 39338937, 2024). "miR-149-5p targets IL-6 in gastric stroma fibroblasts and regulates the cross talk between tumour cells and the tumour stroma." (PMID 38891051, 2024). "There are additional reported effects of IL-6 on tumor cells, specifically regarding the migration and invasion of cancer cells and the acquisition of epithelial-mesenchymal transition (EMT)." (PMID 38510850, 2024).
tumor (continued). "Despite mutant Kras playing a pivotal role in regulating redox homeostasis, IL-6 remains essential for bolstering the antioxidant stress capacity of tumor cells." (PMID 38828409, 2024). "In a CAC mouse model, treatment with IL-6 neutralizing antibodies effectively inhibits chronic intestinal inflammation, while IL-6 knockout reduces tumor burden and significantly promotes IEC apoptosis." (PMID 38516408, 2024). "Our findings suggested that IL-6 or IL-8 can be utilized as independent predictors of efficacy and complement tumor markers CEA, CA50, CA199, and CA724 in predicting the effectiveness of immunotherapy in AGC patients." (PMID 38774604, 2024). "Under cancer conditions, large numbers of IMCs can be pathologically activated by tumour-derived factors such as IL-6 and IL-1β to differentiate into MDSCs." (PMID 39156102, 2024). "Recent studies also suggest that exercise can reduce tumor size and growth in mice by mobilizing IL-6-dependent natural killer cells." (PMID 39337980, 2024). "In SA region, the expression of CRP (P = 0.048), gp-130 (P < 0.001), JAK2 (P = 0.004), and IL-6 (P = 0.001) was lower in tumor tissues compared with normal tissues, while the expression of IL-6R (P = 0.191) and STAT3 (P = 0.960) was comparable." (PMID 38881895, 2024). "Targeting vCAFs or inhibit the IL‐6/IL‐6R axis in tumour cells would be an effective way to reduce the degree of malignancy." (PMID 38158643, 2024). "Existing literature analysis revealed a simultaneous upregulation in TNF-α, IL-6, and IL-1β expression in tumor-bearing mice's hippocampus at that same time point, with mRNA levels aligning with observed plasma cytokine increases." (PMID 39286150, 2024). "Our microarray-based gene expression analysis aimed to investigate the effects of IL-6 on gene expression in primary tumor tissues." (PMID 38510850, 2024). "The IL-6 gene is overexpressed in PCa tissues and cell lines, which increases the production of IL-6 protein and promotes tumour growth and progression." (PMID 39554609, 2024). "This further enhances the production of macrophage-derived interferon (IFN) and interleukin-6 (IL-6), thereby inhibiting immune responses within the tumor microenvironment." (PMID 38461424, 2024). "It is well known that MPE is associated with high levels of IL-6, CCL2, VEGF, TGF-β, and HIF, all of which are associated with maintaining a tumor phenotype resembling stem cells." (PMID 38549044, 2024). "In the tumor microenvironment, IL-6 mediates pro-inflammatory and anti-inflammatory effects via classic signaling." (PMID 39452544, 2024). "Recent studies show that in the treatment of HCC, the combination of IL6 blockers and immunosuppressants can improve the tumor microenvironment, enhance the antitumor effect, and reduce the side effects caused by immunosuppressants." (PMID 39188937, 2024). "This evidence demonstrates that the hormone dysfunction induced by IL-6-driven metabolic reprogramming further influences anti-tumor immunity." (PMID 38828409, 2024). "In contrast, pro-inflammatory IL-1beta and IL-6 were expected to demonstrate active anti-tumour activity." (PMID 38275902, 2024). "The expression of IL-6 was lower in tumor tissues (N = 91) compared with normal tissues (N = 31) (P = 0.049), whereas the expression of STAT3 was higher (P = 0.040)." (PMID 38881895, 2024). "Tumor-derived factors such as IL-3, IL-6, IL-10, TGF-β, platelet-derived growth factor, and granulocyte-macrophage colony-stimulating factor (GM-CSF) promote ROS production in TANs through the STAT3 pathway." (PMID 39795864, 2024). "IL-6 and IL-11 drive tumour cell proliferation, survival, invasiveness and metastasis while suppressing anti-tumour immune responses." (PMID 38600086, 2024). "In fact, as one of the most important sources of IL‐6, fibroblasts have unique spatial properties in the tumor microenvironment." (PMID 39235042, 2024).